ACO2 (aconitase 2)
Diseases named in the same sentence as ACO2 in open-access papers (continued):
Sharing a sentence is not in itself a finding about the gene and the disease.
pulmonary fibrosis (2 papers, 2015 to 2020). Chronic progressive interstitial lung disorder characterized by the replacement of the lung tissue by connective tissue, leading to progressive dyspnea, respiratory failure, or right heart failure. "We reason that the OGG1/ACO-2/SIRT3/mtDNA axis is important in regulating complex cell signaling that promotes pulmonary fibrosis as well as other degenerative disease of the lungs and tumor development." (PMID 26370974, 2015). "Furthermore, additional studies are necessary to assess the translational significance of AEC OGG1 and ACO-2 in preserving mtDNA integrity and preventing pulmonary fibrosis." (PMID 26370974, 2015). "We discuss the emerging role for AEC mtDNA damage repair by 8-oxoguanine DNA glycosylase (OGG1) and mitochondrial aconitase (ACO-2) in maintaining mtDNA integrity, which is important in preventing AEC apoptosis and asbestos-induced pulmonary fibrosis." (PMID 26370974, 2015). "Collectively, these data support a key role for AEC OGG1 and ACO-2 in the maintenance of mtDNA necessary for preventing AEC apoptosis and pulmonary fibrosis." (PMID 26370974, 2015). "We focus on the emerging role for AEC mtDNA damage repair by 8-oxoguanine DNA glycosylase (OGG1) and mitochondrial aconitase (ACO-2) in maintaining mtDNA integrity which is important in preventing AEC apoptosis and asbestos-induced pulmonary fibrosis in a murine model." (PMID 26370974, 2015). "In an asbestos-induced model of pulmonary fibrosis, oxidant-induced mtDNA damage was blocked by overexpression of ACO-2, a mitochondria-targeted OGG1, and an OGG1 mutant incapable of DNA repair that chaperones ACO-2." (PMID 26370974, 2015).
Retinal dystrophy (2 papers, 2023 to 2025). Retinal dystrophy is an abnormality of the retina associated with a hereditary process. "The predominant genes for retinal dystrophy are FDXR, SSBP1, ACO2 and RTN4IP1." (PMID 39423307, 2025).
adenoma (1 paper, 2016). A neoplasm arising from the epithelium. "Further validation was performed by western blot analysis of 3 representative proteins (i.e. ACO2, CES2 and ANXA3), using paired CRC, adenoma and normal fresh-frozen tissues of 3 patients." (PMID 27661117, 2016).
age (1 paper, 2023). A temporal measurement of the time period elapsed since an identifiable point in the life cycle of an organism. "In addition, ACON RNAi flies showed inhibition of autophagy, overexpression of ACO2 in middle-aged flies can prolong life span and improve age-related memory impairment by increasing the expression of Atg8a and reducing the accumulation of p6249." (PMID 38007539, 2023).
atherosclerosis (1 paper, 2024). A disease characterized by the build-up of fatty material and calcium deposition in the arterial wall resulting in partial or complete occlusion of the arterial lumen. "ApoE−/− mice exhibit significantly elevated lipid levels and atherosclerosis indices, with noticeable thickening of the aorta, lipid accumulation, and collagen fiber proliferation, which are associated with reduced expression of FDX1, LA, LIAS, and aconitase 2 (ACO2)." (PMID 39519014, 2024).
cervical cancer (1 paper, 2022). A primary or metastatic malignant neoplasm involving the cervix. "For example, the presence of aconitase 2 (ACO2), IDH1, the subunit G of the IDH3 complex (IDH3G), oxoglutarate dehydrogenase (OGDH) subunit from the oxoglutarate dehydrogenase complex (OGDC) in the nucleus has been described using the human cervical cancer cells HeLa." (PMID 36299478, 2022).
colon cancer (1 paper, 2018). "We stained paraffin sections from colon cancer biopsies of three individuals with antibodies against Aconitase 2 as a reporter of mitochondrial mass and, simultaneously, against one of the proteins Bax, Bcl-2, Bid, Mcl-1, Smac, XIAP, Casp8 and Bar." (PMID 29374163, 2018).
diabetes (1 paper, 2017). "Furthermore, diabetes alters the expression of several genes involved in mitochondrial stress (including mitochondrial membrane pore protein VDAC1, aconitase 2 and heme oxygenase-1) and neuronal injury (such as tyrosine hydroxylase and synaptic protein synaptopodin)." (PMID 28492550, 2017).
glioblastoma (1 paper, 2019). The most malignant astrocytic tumor (WHO grade IV). "In addition to targeting ACO2 in pituitary oncocytoma, miR-127-3p was downregulated in gonadotroph pituitary adenomas and glioblastomas too." (PMID 30945144, 2019).
hereditary spastic paraplegia (1 paper, 2021). Hereditary spastic paraplegias (HSP) comprise a genetically and clinically heterogeneous group of neurodegenerative disorders characterized by progressive spasticity and hyperreflexia of the lower limbs. "Recently, two studies reported rare familial cases of ACO2 variants presenting as complex hereditary spastic paraplegia (HSP) with broad clinical spectra." (PMID 33500398, 2021).
Infertility (1 paper, 2021). "The downregulation of ACO2 and AK1 and the upregulation of YBX1 in sperm from infertile males with severe oligoasthenoteratozoospermia requiring ICSI treatment were identified and compared." (PMID 34213690, 2021). "Moreover, we experimentally validated the downregulation of ACO2 and AK1 and the upregulation of YBX1 in sperm from infertile men." (PMID 34213690, 2021). "Third, the differentially expressed proteins that were validated, namely AK1, ACO2, and YBX1, were not subjected to further in-depth investigation; thus, their roles and mechanisms concerning infertility remain unconfirmed." (PMID 34213690, 2021).
leukemia (1 paper, 2020). A malignant (clonal) hematologic disorder, involving hematopoietic stem cells and characterized by the presence of primitive or atypical myeloid or lymphoid cells in the bone marrow and the blood. "Finally, the Aco2 reduction observed in our experimental set could be an interesting pathway to be investigated in the field of leukemia." (PMID 33081324, 2020). "Therefore, Aco2 could become a new interesting protein to investigate in order to identify a new vulnerable process to target in leukemia cells." (PMID 33081324, 2020).
myocardial infarction (1 paper, 2024). Gross necrosis of the myocardium, as a result of interruption of the blood supply to the area, as in coronary thrombosis. "Our study identified key genes (Aco2, Atp5a1, Ndufs3, and Ndufv1) associated with mitochondrial function in myocardial infarction." (PMID 39775580, 2024). "Ventricular expression of 10 central MitoDEGs (Aco2, Atp5a1, Ndufs3, Ndufv1, Cyc1, Suclg1, Sdha, Sdhb, Cs, and Ndufs2) was verified in a mouse model of myocardial infarction using PCR." (PMID 39775580, 2024). "Besides this, a total of 4 key genes were identified, Aco2, Atp5a1, Ndufs3 and Ndufv1, which were consistent with the expression trend of the mouse myocardial infarction model we constructed." (PMID 39775580, 2024).
nematode infection (1 paper, 2019). "In a comparison between infected and non‐infected roots of wild‐type Arabidopsis plants, we observed that nematode infection is associated with an up‐regulation of SAM synthetase 3 and 4, ACC synthase 7 (ACS7) and ACC oxidase 2 (ACO2), but not ACO3." (PMID 30160354, 2019).
neuropathies (1 paper, 2024). "We identified genes involved in neurophysiological functions as key candidates, constructed a PPI interaction network, and identified key mediating molecules involved in ACO2 mutations causing neuropathies." (PMID 39600307, 2024). "The transcriptome profiling from leukocytes and the transcriptome datasets of cerebellar and retinal organoids retrieved from the GEO database were integrated and analyzed to reveal the key molecules involved in ACO2 pathogenic variants causing neuropathies." (PMID 39600307, 2024). "This study expands the spectrum of pathogenic ACO2 variants, elucidates the potential molecular mechanisms underlying ACO2-related neuropathy, provides in-depth support for the pathogenicity of ACO2 genetic variations, and offers new insights into the pathogenesis of ICRD." (PMID 39600307, 2024). "Pathogenic variants in the ACO2 gene can lead to a wide clinical spectrum of neuropathy." (PMID 39600307, 2024). "In summary, our study identified compound heterozygous variations that expand the spectrum of pathogenic ACO2 variants and revealed key mediating molecules, LRP8 and ANK3, between ACO2 mutations and the development of neuropathy." (PMID 39600307, 2024).
R6 (1 paper, 2017). "Among those differentially-expressed molecules, the aconitase 2 (Aco2) activity was also found to be decreased in the striatum of R6/2 HD mice at late stage and postmortem brains of HD patients." (PMID 29160844, 2017).
schizophrenia (1 paper, 2016). A major psychotic disorder characterized by abnormalities in the perception or expression of reality. "Dysregulation of the Krebs cycle has also been implicated in schizophrenia as a result of differential abundance of several involved enzymes: such as aconitase 2 (ACO2), malate dehydrogenase 1 (MDH1), and citrate synthase (CS)." (PMID 26909022, 2016).
Snyder Robinson syndrome (1 paper, 2019). "Notably, metabolomic analysis increased our diagnostic yield for recessive disease genes by supporting the pathogenicity of missense variants involved in metabolic pathways, as illustrated for Snyder Robinson syndrome and ACO2 deficiency." (PMID 30552426, 2019).
tumor (17 papers, 2012 to 2025). "FH-deficient cells harbor lower fumarate and preserve Aconitase 2 (ACO2) function to promote tumor progression." (PMID 36778129, 2023). "According to our analysis of TCGA data, there were significant statistical associations in ACO2 expression according to tumor stage, prognosis, and diagnosis in HCC." (PMID 36531056, 2022). "KEGG data suggested that ACO2 regulates tumor progression by affecting molecular pathways involved in cellular energy metabolism and metabolite changes." (PMID 36531056, 2022). "Expression meta-analysis in 8 studies was obtained using the Oncomine database, and ACO2 expression was generally down-regulated in tumor tissue compared with normal tissue." (PMID 34790035, 2021). "In our study, clinicopathological parameter sage, tumor stage, lymphatic, hematogenous metastases and SUCLG2, SUCLG1, ACLY, SUCLG2P2, ATIC and ACO2 genes were found to be associated with survival in univariable or multivariate analysis." (PMID 34589110, 2021). "The results showed that the three variables SUCLG2P2, ACO2 genes and clinicopathological parameter stage were different between the normal group and the tumor group." (PMID 34589110, 2021). "We concluded that the tumor suppressor role of miR-127-3p and miR-744-5p can be mediated at least partly through regulation of ACO2." (PMID 30945144, 2019). "Interestingly, expression of ACO2 H73N showed a distinct inhibition of tumor growth in the intraocular xenograft mouse model." (PMID 40988976, 2025). "In tumor cells harboring mutant FH, an accumulation of fumarate results in succination of cysteine-modifying proteins such as kelch-like ECH-associated protein 1 (KEAP1) and mitochondrial aconitase (ACO2)." (PMID 28748451, 2018). "Downregulation of proteins involved in the mitochondrial respiratory chain like NFU1, ACO2, PDHA1, and proteins like DECR1, CNDP2, and SPINT1, which have a tumor suppressive role in different cancers were noted." (PMID 34885041, 2021). "Consistent with this premise, tumor cells most sensitive to these agents exhibit over expression of TCA-related discriminating genes, IDH3A, IDH1, IDH3G, ACO2 and ACLY." (PMID 23056181, 2012). "Genes involved in glycolysis (ALDOA, LDHA, PGK1, PFKL, PGM1) and other metabolic processes (GPX4, PRDX4, ACO2, ASPH, IDH2, SQLE, NPC2, SPTSSA) were upregulated in primary tumor cells, suggesting that the metabolism in primary tumors was distinct from that in their matched metastasis." (PMID 39225101, 2024). "As expected, ACO2 depletion in PaTu-8988t cells with depletion of IscU2 or KRAS increased citrate level, suggesting that ACO2 plays a role in regulation of citrate production in tumor cells expressing activated KRAS." (PMID 37488138, 2023). "Among them, ACO2 was upregulated in most cancers, such as BRCA, CESC, CHOL, and DLBC, and five forms of cancer showed downregulation between tumor and nontumor tissues (ACC, BLCA, GBM, KIRC and LAML)." (PMID 36531056, 2022).
cancer (13 papers, 2011 to 2025). A tumor composed of atypical neoplastic, often pleomorphic cells that invade other tissues. "ACO2 gene alterations, including mutations, duplications, and amplifications, were identified in a wide variety of cancer types." (PMID 36531056, 2022). "Lastly, isoTWAS identifies 52 genes (34 undetected by TWAS) that are associated with five or more cancer outcomes, including multiple known oncogenes or tumor suppressor genes, such as MYC, MUTYH, GNAI2, ACO2, and BMI1." (PMID 40775447, 2025). "JUN, CXCR4, and WNT5A were the top three interaction DEGs in pathways in cancer; H6PD, FH, and ACO2, which associate with glucose metabolism, were the top three interaction DEGS in metabolic processes." (PMID 37601754, 2023). "It has been reported that the mutations in DNA2, ACO2, and ATP7A were correlated with the initiation or poor clinical outcomes of cancers." (PMID 36685880, 2022). "We found that in the first three steps of the TCA cycle, digital expression of aconitase 2 (ACO2) in the brain exceeded both citrate synthase (CS) and isocitrate dehydrogenase 2 (IDH2), while in cancer cells this trend was quite the opposite." (PMID 22166000, 2011). "Aconitase 2 (ACO2) participates in the TCA cycle by converting citrate to isocitrate, but no evident demonstrations of its involvement in cancer metabolism have been provided so far." (PMID 31819175, 2020).
neurodegenerative disease (9 papers, 2009 to 2024). A disorder of the central nervous system characterized by gradual and progressive loss of neural tissue and neurologic function. "Inactivation or dysfunction of Aco2 as well as mutations found in the ACO2 gene appear to be significant factors in the development and promotion of various types of neurodegenerative diseases." (PMID 39337438, 2024). "Mutations in ACO2 have been described in association with early fatal or neurodegenerative diseases." (PMID 38668366, 2024). "Mutations in ACO2 have been described in the context of early fatal or neurodegenerative disease in homozygous or compound heterozygous state." (PMID 33028849, 2020). "Infantile cerebellar-retinal degeneration associated with mutations in the mitochondrial aconitase 2 gene (ACO2) has been recently described as a neurodegenerative disease of autosomal recessive inheritance." (PMID 28463998, 2017). "Additional support for a protective role of ACO-2 is that ACO-2 inactivation has been linked to decreased lifespan in yeast and progressive neurodegenerative diseases in humans." (PMID 26370974, 2015). "The role of Aco2 in the pathogenesis of some neurodegenerative diseases is highlighted." (PMID 39337438, 2024). "TID1S448-453 may be beneficial for a number of neurodegenerative diseases, including FRDA, which have a mitochondrial biogenesis deficit and aconitase 2 deficient disorders." (PMID 38495102, 2024). "However, Aco2 activity has been studied in peripheral blood in other neurodegenerative diseases." (PMID 37240666, 2023).
infection (4 papers, 2010 to 2023). The state of being infected such as from the introduction of a foreign agent such as serum, vaccine, antigenic substance or organism. "We found that oxaloacetate decreased the induction of six selected ATFS-1 targets caused by aco-2 RNAi upon PA14 infection." (PMID 37349299, 2023). "We genetically inhibited mammalian ACO2 using siRNA knockdown (ACO2 KD), and found that ACO2 KD increased the viability of HeLa cells upon infection with pathogenic S. aureus, consistent with the data using C. elegans." (PMID 37349299, 2023). "Because simply disrupting normal mitochondrial physiology may lead to protection against infection in general, we compared transcriptome changes caused by aco-2 RNAi with those by other mitochondrial dysfunctions." (PMID 37349299, 2023). "We then categorized the genes that were differentially expressed by PA14 infection and/or aco-2 RNAi into four groups (d: Groups i to iv)." (PMID 37349299, 2023). "Together, these data suggest that knockdown of aco-2 results in a robust transcriptomic response to pathogen infection compared with other implementations that disrupt mitochondrial physiology." (PMID 37349299, 2023). "Consistent with our transcriptome analysis, we found that the majority of selected targets of PMK-1/ATF-7 and ATFS-1 were upregulated by both PA14 infection and aco-2 RNAi." (PMID 37349299, 2023). "Group iii included 4 genes downregulated by aco-2 RNAi, for which PA14 infection increased the expression, and Group iv contained 60 genes downregulated by aco-2 RNAi whose expression was decreased by PA14 infection." (PMID 37349299, 2023). "We found that, upon infection with S. aureus, ACO2 KD further increased the expression of HSPD1, HSPA9, and CLIPP, three of four selected targets of ATF5, a key mediator of the UPRmt and the mammalian ortholog of C. elegans ATFS-1, in HeLa cells." (PMID 37349299, 2023). "Group i consisted of 798 genes upregulated by aco-2 RNAi whose expression was increased by PA14 infection." (PMID 37349299, 2023). "Group ii included 297 genes upregulated by aco-2 RNAi whose expression was decreased by PA14 infection." (PMID 37349299, 2023). "And the result showed that ACS3 and ACO2 had high expression levels in wild tomato LA1777 under On-lz infection." (PMID 35163190, 2022). "For example, we showed that aconitase 2 (ACO2) was significantly reduced in the late infection stages (24–120 h) in PBMCs and BALF." (PMID 34952961, 2021). "Together with our RNA seq analysis, these data suggest that protection against pathogen infection by aco-2 RNAi is a specific process, which does not seem to be caused by generally disrupting normal mitochondrial physiology." (PMID 37349299, 2023). "Among them, RNAi targeting aconitase 2 (aco-2), which encodes mitochondrial aconitase that catalyzes the conversion of citrate to isocitrate, greatly increased the survival of animals upon infection with Pseudomonas aeruginosa PA14, Gram-negative pathogenic bacteria (up to 102%)." (PMID 37349299, 2023). "We found that the expression levels of PAL4 and ICS were decreased in wild tomato LA1777 under On-lz infection, while the expression levels of ACS3 and ACO2 were increased in wild tomato LA1777 under On-lz infection." (PMID 35163190, 2022). "We asked whether mitochondrial aconitase ACO2, the mammalian ortholog of ACO-2, affected immune responses during pathogen infection." (PMID 37349299, 2023). "We found that mutations in skn-1, daf-16, hlh-30, zip-2, or hsf-1 partially suppressed the increased survival of aco-2 RNAi-treated animals upon PA14 infection, or had nonspecific effects." (PMID 37349299, 2023). "In contrast, three selected targets of SKN-1/NRF, whose knockdown overlapped in both directions in our comparison with Group i genes, were upregulated by aco-2 RNAi, but not by PA14 infection." (PMID 37349299, 2023).
infection (continued). "We identified no less than 8 enzymes (ACO-2, F53F4.10, W02F12.5, FUM-1, IDH-2, SDHA-1, CTS-1, F23B12.5) that are part of the citric acid cycle which might reflect the need for extra energy whilst fighting off an infection." (PMID 20163716, 2010).